GDI2 (GDP dissociation inhibitor 2)
Diseases named in the same sentence as GDI2 in open-access papers (continued):
Sharing a sentence is not in itself a finding about the gene and the disease.
cancer (13 papers, 2009 to 2026). A tumor composed of atypical neoplastic, often pleomorphic cells that invade other tissues. "Further studies are needed to fully understand the molecular mechanisms underlying GDI2’s functions and its potential as a therapeutic target in cancer and immune-related diseases." (PMID 39831280, 2024). "In cancer, dysregulation of GDI2 contributes to altered tumor cell-macrophage interactions, promoting inflammation and metastasis, with GDI2 acting as a metastasis suppressor in certain cancers." (PMID 39831280, 2024). "This review emphasizes the need for further research to elucidate the molecular mechanisms of GDI2 and its potential as a therapeutic target in developmental disorders, cancer, and immune-related diseases." (PMID 39831280, 2024). "This review highlights the importance of GDI2 in various biological processes, particularly embryonic development, apoptosis regulation, cancer, and immune responses." (PMID 39831280, 2024). "The GDI2 gene is upregulated in various cancers and can regulate biological functions, including tumor cell proliferation, apoptosis, migration, and cell metabolism." (PMID 39323841, 2024). "In the results of immunohistochemistry experiments, the expression of GDI2 in tumor tissues was significantly higher than that in normal tissues adjacent to cancer (P < 0.05)." (PMID 39323841, 2024). "This review aims to discuss the novel findings from recent studies on GDI2, particularly its role in embryonic development, apoptosis regulation, and its implications in cancer and immune responses." (PMID 39831280, 2024). "Dysregulation of GDI2 has been reported in many different cancers, including pancreatic carcinoma, ovarian cancer, gastric cancer, thyroid carcinoma, hematopoiesis and leukemogenesis and esophageal squamous cell carcinoma." (PMID 39831280, 2024). "The qRT-PCR results showed that the mRNA expression level of GDI2 in CRC tumor tissues was higher than that in normal tissues adjacent to the cancer (P < 0.01)." (PMID 39323841, 2024). "GDI2 expression is abnormal in many cancer types, including pancreatic, ovarian, gastric and oesophageal squamous cell carcinomas." (PMID 34760691, 2021). "Abnormal expression of the GDI2 gene has been demonstrated in many cancer types." (PMID 39323841, 2024). "Finally, we conducted a comprehensive evaluation of gene sets using GSVA and we found that the DARS/GDI2/P4HA2/TRUB1 gene sets are closely related to the occurrence of cancer." (PMID 35111402, 2022). "Finally, GSVA analysis found that DARS/GDI2/P4HA2/TRUB1 gene sets are closely related to the occurrence of cancer." (PMID 35111402, 2022). "The high expression of RhoGDI2 found in this study could possibly be explained by detection of these diseases at an early stage of cancer progression before downregulation of the GDP dissociation inhibitor 2 gene." (PMID 19367286, 2009). "An examination of publicly available (TCGA) human RNA-seq data, CNA, and methylation revealed that NF2 and TAOK1 are deleted and under-expressed, the GDI2 promoter is hypermethylated, and APC is lost in a subset of human cancers." (PMID 33808166, 2021). "For several genes, most notably CNOT7, GDI1 and SLC25A37, there are a subset of tumours that showed homozygous deletion and thus inhibition/suppression of CNOT8, GDI2 or SLC25A28, respectively, would be predicted to provoke cellular lethality/reduced cancer cell fitness." (PMID 40968372, 2025). "Similarly, proteins involved in the inhibition of cancer invasion are highly upregulated (fold change ≥ 1) in NVA-AA-treated MDA-MB-231 cells, e.g., lumican (LUM), along with proteins involved in vesicular trafficking, e.g., Rab GDP dissociation inhibitor beta (GDI2)." (PMID 37719007, 2023).
tumor (13 papers, 2014 to 2025). "Since loss of GDI2 alters tumor cell-macrophage receptor crosstalk to enhance both local inflammation and tumor cell invasion and growth, leading to secretion of inflammatory cytokines by macrophages." (PMID 39831280, 2024). "In tumor cells, loss of GDI2 alters tumor cell-macrophage receptor crosstalk to enhance both local inflammation and tumor cell invasion and growth, leading to secretion of inflammatory cytokines by macrophages that promote metastatic growth of tumor cells." (PMID 39831280, 2024). "Further TIMER analysis indicated that the immune system had a good effect on tumor microenvironment, and that the mutations of DARS / GDI2/P4HA2/TRUB1 had important application value in tumor immunology." (PMID 35111402, 2022). "The loss of GDI2 led to increased migration in a transwell assay and tumor formation in a xenograft model." (PMID 33808166, 2021). "In conclusion, GDI2 expression was explored to be elevated in HCC tumor tissues and associated with poor prognosis in HCC patients from our TCGA study for the first time." (PMID 34894398, 2021). "In addition, gene GDI2 has been linked to a number of biological processes, including induction of antibodies against different types of human tumor cells and embryonic development." (PMID 40268997, 2025). "The results of clinical information analysis showed that the expression level of GDI2 was significantly correlated with the presence of metastasis (P = 0.0121), lymphocyte count (P = 0.0018), and tumor volume size (P < 0.05)." (PMID 39323841, 2024). "Initial analyses revealed that mRNA expression of ITGB6, ERBB2, RAB5A, RAB7A, and GDI2 was all significantly higher in tumor tissue in comparison to normal tissue." (PMID 39630893, 2024). "Having established the impact of RAB5, RAB7A, and GDI2 on cellular invasion through FN-rich collagen matrices, we sought to analyze their role in early tumor dissemination events in vivo." (PMID 39630893, 2024). "No existing studies demonstrate a direct biological link between GDI2 and telomere length, yet they are both involved in a complex network of tumor development." (PMID 38431573, 2024). "The expression level of GDI2 correlated with clinical characteristics such as lymphatic metastasis, tumor stage, tumor volume, and lymphocyte count." (PMID 39323841, 2024). "As a result, high expression of GDI2 turned out to be correlated with advanced tumor status and poor prognosis." (PMID 34894398, 2021). "Individual loss-of-function mutations in the TAOK1, GDI2, NF1, and APC genes resulted in transformation of immortalized human Schwann cells and tumor formation in a xenograft model." (PMID 33808166, 2021). "Both enrichment and immune infiltration analyses implied that GDI2-associated signaling mainly involve lipid metabolism and extracellular matrix (ECM) constructing pathways related to tumor microenvironment (TME) (P < 0.05)." (PMID 34894398, 2021). "Among them, 50 tumor-and-adjacent paired samples were also showed high expression of GDI2 in tumor compared with paired normal tissues (P < 0.001)." (PMID 34894398, 2021). "Although this observation is consistent with a selective growth advantage conferred to cells by ARNT and GDI2, larger sets of primary-metastatic tumor pairs will be needed to verify this trend." (PMID 25059231, 2014). "Considering the LMD-promoting effects of Arnt and Gdi2, we predicted that these genes would confer to tumor cells a set of traits that enable them to detach from the tumor mass, survive a transit phase in the CSF, and ultimately colonize the leptomeninges." (PMID 25059231, 2014). "These analyses demonstrated that siRNA-mediated GDI2 inhibition exerts differential effects on haptotactic cell migration on FN and invasion, suppressing αVβ6-dependent motility but promoting tumor cell invasion." (PMID 39630893, 2024).
tumor (continued). "GDI2 controls the activity of Rho GTPase’s pathway to regulatory guanine nucleotide exchange factor and GTPase activating protein, and may play a role in tumor cell apoptosis." (PMID 35111402, 2022). "Our study demonstrated that silencing GDI2 in CRC cells reduces their proliferative activity, migration, and invasive capabilities as well as in vivo tumor growth inhibition." (PMID 39323841, 2024). "On the other hand, GDI2, a negative regulator of Rho signaling, is hypermethylated at its promoter, as found in MPNST human tumor samples." (PMID 33808166, 2021). "Based on the specific bioinformatics analyses on GDI2 based on The Cancer Genome Atlas (TCGA)-LIHC database, our results figured out that the GDI2 significantly over-expressed in tumor tissues of HCC patients compared with normal tissues, acting as a tumor booster in HCC progression." (PMID 34894398, 2021). "By conferring to tumor cells the ability to proliferate without surface attachment, Arnt and Gdi2 favor the formation of stable colonies of cells capable of seeding the leptomeninges." (PMID 25059231, 2014). "By making tumor cells competent to proliferate without surface attachment, expression of Arnt and Gdi2 would also favor the formation of suspended colonies of cells capable of surviving in the CSF before reimplanting on a leptomeningeal surface." (PMID 25059231, 2014). "As for the clinicopathological correlation for HCC patients, it was found that the expression of GDI2 was increased as the disease progressed, especially for the HCC patients in late T stage, advanced pathologic stage, poor histologic grade, and with bad tumor status (*P < 0.05)." (PMID 34894398, 2021). "This subset of proteins was particularly enriched in proteins involved in tumor metastasis and malignancy, such as proteins from the canonical actin cytoskeleton signaling, including several members of the RhoA/RhoGDI signaling pathway (ACTR2, EZR, MSM, PFN, GDI2)." (PMID 29872504, 2018). "Additionally, GDI2, a protein functioning in the cycling of Rab GTPases and arginase II, i.e. a non-liver isoform of the urea cycle were up-regulated in tumours of EGF transgenic mice." (PMID 25872475, 2015).
bacterial infection (1 paper, 2024). "Recent findings suggest that GDI2 plays a role in the immune response during bacterial infections." (PMID 39831280, 2024). "Under normal conditions, GDI2 binds to the ITIM domain of Siglec-G, whereas Rab1a is recruited to the ITIM domain during bacterial infection." (PMID 39831280, 2024).
GDI2 also shares sentences with these, for which no sentence is quoted: anaplastic thyroid cancers (1 paper); cardiac diseases (1); cholangiocarcinoma (1); COVID-19 (1); esophageal squamous cell carcinoma (1); glioblastoma (1); Hepatic fibrosis (1); idiopathic pulmonary fibrosis (1); Insulin resistance (1); liver cirrhosis (1); lung adenocarcinoma (1); multiple sclerosis (1); Obesity (1); rectal cancer (1); Uterine leiomyoma (1).